APOE (apolipoprotein E)
Diseases named in the same sentence as APOE in open-access papers (continued):
Sharing a sentence is not in itself a finding about the gene and the disease.
Alzheimer disease (continued). "The most common genetic risk factor for dementia is Apolipoprotein E (APOE), with the ε2 allele being protective against Alzheimer’s dementia and the ε4 allele greatly increasing risk." (PMID 36477264, 2022). "APOE ɛ4 is the major genetic risk factor of late onset Alzheimer’s disease (AD) and has been associated with cognition in other synucleinopathies like dementia with Lewy bodies (DLB)." (PMID 36508411, 2022). "Here the APOE locus stood out in terms of number of enriched phenotypes, with its regulated proteins being enriched for associations with Alzheimer’s disease, AMD, and numerous cardiometabolic traits including coronary artery disease." (PMID 35078996, 2022). "Apart from that, Apolipoprotein E4 (APOE4), a variant of apolipoprotein, was also known to be a risk factor of Alzheimer’s disease due to their ineffectiveness in promoting the proteolytic breakdown of Aβ." (PMID 36079752, 2022). "Our MR analyses demonstrated that Alzheimer’s disease is causally associated with increased hip fracture risk, and a sensitivity study excluding the genome-wide significant hip fracture signal at the APOE locus revealed a similar causal association." (PMID 36260985, 2022). "APOE and Alzheimer Disease Meta Analysis Consortium Effects of age, sex, and ethnicity on the association between apolipoprotein E genotype and Alzheimer disease." (PMID 35866735, 2022). "Apolipoprotein (APOE) is a major risk factor of Alzheimer’s disease (AD), with the E2, E3 and E4 isoforms differentially regulating the burden of AD-associated neuropathologies, such as amyloid β and tau." (PMID 35440098, 2022). "Human APOE4 (apolipoprotein E4 isoform) is a powerful genetic risk factor for late-onset Alzheimer disease (AD)." (PMID 38912292, 2022). "Our objective in this study was to identify areas of the genome that interact with ApoE ε4 in African ancestry and result in a lower risk for developing Alzheimer disease." (PMID 35788729, 2022). "An analysis of UK Biobank data identified the ApoE e4e4 genotype, which is associated with dramatically increased risk of Alzheimer’s disease, as being associated with COVID-19 test positivity and severity." (PMID 36671431, 2022). "The apolipoprotein E4 (APOE4) variant is the strongest genetic risk factor for Alzheimer disease (AD), while the APOE2 allele is protective." (PMID 34919811, 2022). "The Apolipoprotein E-ε4 allele (APOE-ε4) is the strongest genetic risk factor for late onset Alzheimer disease (AD)." (PMID 36436561, 2022). "ApoE variants are known to affect Alzheimer’s disease risk, with the APOE4 isoform conferring a significantly increased risk." (PMID 36289910, 2022). "The most significant genetic risk factor for developing late-onset Alzheimer’s disease (AD) is the ε4 allele of apolipoprotein E (APOE4)." (PMID 36457019, 2022). "The apolipoprotein E (APOE) ε4 allele is the main genetic risk factor for dementia and Alzheimer's disease (AD), but the underlying mechanism for the increased risk is not well understood." (PMID 35912087, 2022). "Multiple risk factors for Alzheimer’s disease (AD) have been identified, such as possession of the apolipoprotein E4 (ApoE4) allele, biological sex, and dietary patterns contributing to the increasing worldwide incidence of AD through complex interactions." (PMID 35409283, 2022). "The Apolipoprotein E (APOE) genotype has been shown to be the strongest genetic risk factor for Alzheimer’s disease (AD)." (PMID 35347084, 2022). "Further, in our regional analysis of white-matter hyperintensities, Alzheimer’s disease-polygenic risk score beyond APOE is predictive of white-matter volume in the occipital lobe in Alzheimer’s disease subjects in the polygenic regime." (PMID 36523268, 2022). "Because of this, strong correlations between nucleotide polymorphisms of TOMM40 and Alzheimer’s disease have commonly been attributed to the transposition of APOE/TOMM40 regulatory elements." (PMID 36517509, 2022).
Alzheimer disease (continued). "That said, AD-PRS beyond APOE is correlated with white-matter load in the occipital lobe in Alzheimer’s disease subjects upon the inclusion of many variants (polygenic P = 0.5)." (PMID 36523268, 2022). "Apolipoprotein E ε4 (APOE4) is the primary genetic risk factor for the late-onset form of Alzheimer’s disease (AD)." (PMID 35351864, 2022). "Carriers of the APOE ε4 allele are at a 5 to 15-fold higher risk of developing Alzheimer’s disease (AD) while the APOE ε3 allele is considered AD risk-neutral and ε2 protective." (PMID 36002891, 2022). "The APOE Ɛ4 allele is a key genetic risk factor for late-onset Alzheimer’s disease, and an interaction between free testosterone and APOE Ɛ4 genotype has been reported." (PMID 35633431, 2022). "The study of polygenic risk suggests that many small effect size Alzheimer’s disease variants beyond APOE are a predictor of atrophy acceleration in healthy individuals (and perhaps also MCI subjects)." (PMID 36523268, 2022). "The ε4 allele of APOE (APOE4) constitutes the major susceptibility gene for late-onset Alzheimer’s disease (AD), and, in fact, it has been associated with both decreased neuroprotection and increased neurotoxicity." (PMID 36499600, 2022). "As a previously unreported finding, we showed that the protective effect of methotrexate in Alzheimer’s disease is observed only in those who carry at least one APOE ε4 allele." (PMID 37118290, 2022). "This suggests that any Mendelian randomization evidence for a causal effect of LDL cholesterol on Alzheimer disease risk is dependent on the variants in the APOE gene region." (PMID 35452592, 2022). "The ε4 allele of apolipoprotein E (APOE) is an important genetic risk factor for Alzheimer’s disease (AD)." (PMID 36611808, 2022). "In fact, people with one ε4 allele have about a three-fold increased risk of Alzheimer’s disease, and those with two ε4 alleles have about a 15-fold increased risk, compared with those with the most common genotype, APOE ε3ε3." (PMID 35242026, 2022). "Possession of the ε4 allele of apolipoprotein E (APOE) is the primary genetic risk factor for late-onset Alzheimer’s disease (AD)." (PMID 35351864, 2022). "A stable cardiovascular risk trajectory appeared to partially mitigate Alzheimer disease dementia risk for APOE ε4 carriers." (PMID 35444051, 2022). "Humanized mouse models expressing these three major human APOE isoforms (targeted replacement) can also be used to model genetic risk for late onset Alzheimer’s disease." (PMID 35784847, 2022). "This was particularly evident for Alzheimer’s disease, where the enrichment was entirely driven by the associations of proteins regulated by the APOE locus." (PMID 35078996, 2022). "The APOE ε4 allele is well known to be associated with an increased risk of developing Alzheimer’s disease." (PMID 35205665, 2022). "With this in mind, we investigated the impact of risk factors for Alzheimer’s dementia, such as APOE-ε4 genotype, older age and female sex on the relationship between CSF and PET markers of Aβ." (PMID 35236958, 2022). "APOE‐ε4, a major risk factor for Alzheimer's disease, has the lowest lipid binding efficiency compared with other APOE isoforms." (PMID 35388616, 2022). "By leveraging the power of the approximately 40,000 participants of the UK Biobank cohort, we assessed impacts from the protective APOE ɛ2 and the deleterious APOE ɛ4 Alzheimer’s disease alleles on these structural relationships." (PMID 36512526, 2022). "The APOE ɛ4 allele that is associated with high risk of Alzheimer’s disease is also associated with low plasma HDL cholesterol concentrations." (PMID 36077172, 2022). "In a subcohort with available miRNA data subjects with current depressive symptoms and carrying APOE e4 revealed reduced levels of hsa-miR-107, a prominent risk marker for early Alzheimer’s Disease." (PMID 35884866, 2022).
Alzheimer disease (continued). "In recent research, hypoxia-induced miR-210 was shown to target synaptic function genes (GRINA, TMUB1, and AP2S1), plasticity genes (ACTB), Alzheimer’s disease genes (APOE), and genes implicated in MAPK/VEGF and OXPHOS signaling pathways." (PMID 35626359, 2022). "In contrast, another minor apoE variant with a V236E mutation in the C-terminal domain is associated with reduced risk of Alzheimer’s disease." (PMID 36077289, 2022). "Astroglia play an important role, providing de novo synthesized cholesterol to neurons in the form of ApoE-lipidated particles; disruption of this process can increase the risk of Alzheimer’s disease." (PMID 35955777, 2022). "Its gene is located on chromosome 19 and is encoded by three alleles, namely ApoE-ε2, ApoE-ε3, and ApoE-ε4, of which ApoE-ε4 is the largest genetic risk factor for Alzheimer's disease (AD)." (PMID 35317127, 2022). "African descent populations have a lower Alzheimer disease risk from ApoE ε4 compared to other populations." (PMID 35788729, 2022). "The correlation of APOE gene polymorphisms and the risk of cerebral vascular and degenerative diseases have been investigated a lot, especially in Alzheimer's disease (AD) and cerebral amyloid angiopathy (CAA)." (PMID 35154509, 2022). "These variants (rs634869 and rs12525163) are both in the APOE gene region, a locus known to be a strong predictor of Alzheimer disease." (PMID 35452592, 2022). "The ε4 allele of the apolipoprotein E (APOE4+) genotype is a major genetic risk factor for Alzheimer’s disease (AD), but the mechanisms underlying its influence remain incompletely understood." (PMID 35979332, 2022). "The APOE-ε4 allele is known to predispose to amyloid deposition and consequently is strongly associated with Alzheimer's disease (AD) risk." (PMID 35977442, 2022). "We use 730 subjects from the Alzheimer’s disease neuroimaging initiative database to investigate polygenic risk score effects (beyond APOE) on whole-brain volumes, total and regional white-matter hyperintensities and amyloid beta across diagnostic groups." (PMID 36523268, 2022). "The apolipoprotein E (apo-E) is a key regulator of lipid metabolism and represents a risk factor for cardiovascular diseases and Alzheimer’s disease." (PMID 35205153, 2022). "Apolipoprotein E epsilon 4 (APOE-ε4) carrier status is an established risk factor for Alzheimer’s disease (AD) dementia." (PMID 35354468, 2022). "In human post-mortem tissue and mouse models humanized for apolipoprotein E, apolipoprotein E4, the greatest genetic risk factor for Alzheimer’s disease, drives an age-dependent lowering of the exosome levels in the brain extracellular space." (PMID 35501523, 2022). "Having a family history (FH+) of Alzheimer’s disease (AD) and being a carrier of at least one ɛ4 allele of the ApoE gene are two of the main risk factors for the development of AD." (PMID 35629270, 2022). "APOLIPOPROTEIN E*4 (APOE*4) is the strongest genetic risk factor for late-onset Alzheimer’s disease (AD)." (PMID 35120553, 2022). "Our findings support previous findings indicating that people with one or more APOE ε4 alleles are likely to have more impaired sleep but add to these findings by controlling for the severity of Alzheimer’s disease pathology as determined neuropathologically." (PMID 35354468, 2022). "Among the genetic factors, the ε4 allele of apolipoprotein E (APOE) has the strongest impact on the risk of developing late-onset Alzheimer’s disease (LOAD), the most common form of AD." (PMID 36430248, 2022). "The apolipoprotein E (APOE) ε4 allele confers the strongest risk for late-onset Alzheimer’s disease (AD) besides age itself, but the mechanisms underlying this risk are debated." (PMID 35768831, 2022). "Apolipoprotein E (ApoE) polymorphism is the most susceptible genetic factor for late-onset Alzheimer’s disease (AD), which is located on chromosome 19, composed of 299 amino acids." (PMID 36578446, 2022).
Alzheimer disease (continued). "Individuals afflicted with AD carrying the ApoE gene markedly increase the risk of late-onset Alzheimer’s disease (AD)." (PMID 35454088, 2022). "The APOE gene is the strongest genetic risk factor for Alzheimer’s disease (AD) with the ε4 allele increasing the risk by 2-4 folds compared to the most common ε3 allele." (PMID 35922805, 2022). "The single most important genetic risk factor for Alzheimer’s’ disease (AD) and cognitive decline is Apolipoprotein E (APOE)." (PMID 35160273, 2022). "Increased expressions of Crystallin Alpha B (Cryab) and apolipoprotein E (ApoE) have been associated with protective reactive gliosis in neurodegenerative diseases such as Parkinson’s disease (PD), Alzheimer’s disease (AD), and Multiple Sclerosis (MS)." (PMID 36457352, 2022). "Previous studies on Alzheimer’s disease (AD) showed that amyloid β (Aß) deposits and atrophies in the hippocampus are associated with memory impairments but also with apolipoprotein E (APOE) ε4 status." (PMID 35884866, 2022). "For example, in Alzheimer's disease (AD), a few common genetic factors, such as the ε4 allele of apolipoprotein E (APOE) confers a strong risk." (PMID 35832601, 2022). "The ε4 allele of apolipoprotein E (APOE ε4) is the strongest known genetic risk factor for late-onset Alzheimer’s disease (AD), associated with amyloid pathogenesis." (PMID 36284363, 2022). "It has been suggested that diabetes mellitus (DM) and the apolipoprotein E (APOE) ε4 allele (APOE4) increase the risk for Alzheimer’s disease (AD) and cognitive decline." (PMID 36466611, 2022). "Two main genetic risks for sporadic Alzheimer’s disease (AD) are a family history and ɛ4 allele of apolipoprotein E. The brain and retina are part of the central nervous system and share pathophysiological mechanisms in AD." (PMID 35659054, 2022). "Restrictions on existing APOE mouse models have impacted research toward understanding the strongest genetic risk factor contributing to Alzheimer’s disease (AD) and dementia, APOEε4, by hindering observation of a key, common genotype in humans – APOEε3/ε4." (PMID 35370604, 2022). "An important breakthrough in our understanding of Alzheimer’s disease (AD) was the identification of the apolipoprotein E APOE-ɛ4 allele as a risk factor." (PMID 36324176, 2022). "Apolipoprotein ε4 (APOE ε4) is the largest genetic risk factor for late-onset Alzheimer’s disease (AD)." (PMID 36550123, 2022). "With age the apolipoprotein E (APOE) E4 allele (involved in lipid homeostasis) is associated with perturbation of bioenergetics pathways in Alzheimer’s disease (AD)." (PMID 36688151, 2022). "Specifically, it was applied to late-onset Alzheimer's disease (AD) patients that paradoxically carried the AD-protective APOE ɛ2 allele compared to healthy individuals that carried the AD-risk APOE ɛ4 allele." (PMID 35488922, 2022). "APOE4 is the strongest common genetic risk factor for the development of Alzheimer’s disease (AD); however, a fundamental understanding of its role in AD has been confounded by the pleiotropic nature of the APOE gene." (PMID 35565665, 2022). "The apolipoprotein E (ApoE) gene (19q13.32) is the strongest genetic risk factor for late-onset Alzheimer disease (AD) and is associated with an earlier age-of-onset." (PMID 35788729, 2022). "Apolipoprotein (APOE) is implicated and verified as the main risk factor for early-onset Alzheimer's disease (AD)." (PMID 35756922, 2022). "Results of this study suggest that the APOE ɛ4 allele can modulate both the clinical expression and the biomarkers of Alzheimer disease in a genetic form of the disease, such as in Down syndrome." (PMID 34228042, 2021). "Our recent findings link the apolipoprotein E4 (ApoE4)-specific changes in brain phosphoinositol biphosphate (PIP2) homeostasis to the susceptibility of developing Alzheimer’s Disease (AD)." (PMID 32632205, 2021).
Alzheimer disease (continued). "The presence of the APOE e4 allele has been associated with increased risk for the development of Alzheimer’s disease and with traumatic brain injuries as well." (PMID 34970595, 2021). "A family history (FH+) of Alzheimer’s disease (AD) and ɛ4 allele of the ApoE gene are the main genetic risk factors for developing AD, whereas ɛ4 allele plays a protective role in age-related macular degeneration." (PMID 34199664, 2021). "Fewer studies have examined the association between APOE e4 status on hippocampal subfield volume than the effect of Alzheimer’s disease itself." (PMID 33615215, 2021). "As the ε4 allele of the APOE gene is the single causal variant associated with late-onset Alzheimer's disease risk and nearly 75% of all dementia cases are Alzheimer's disease cases, APOE ε4 allele status also was included in the current study." (PMID 34603367, 2021). "Among the three alleles for ApoE, the presence of ApoE4 is considered an important genetic risk factor for Alzheimer’s disease, leading to tau hyperphosphorylation in an Aβ-dependent manner." (PMID 33672982, 2021). "Twin studies have shown that Alzheimer’s disease, the most common form of dementia, is highly heritable, with the apolipoprotein E (APOE) ɛ4 allele being the strongest genetic risk factor." (PMID 34657626, 2021). "The E4 variant of APOE (APOE4) is known as a main susceptibility gene for Alzheimer’s disease and leads to accelerated breakdown of the BBB." (PMID 34203960, 2021). "In terms of biological plausibility, APOE genotype has long been associated with cardiovascular disease, dementia, and Alzheimer’s disease." (PMID 34193248, 2021). "The most significant known genetic risk factor for sporadic or late-onset Alzheimer’s disease (AD) is an allele variant of apolipoprotein E (ApoE), a protein involved in lipid metabolism and cholesterol homeostasis." (PMID 34071762, 2021). "The relationship between APOE polymorphisms and the development of Alzheimer’s disease is well studied, and the APOE E4 allele is a risk factor for Alzheimer’s disease." (PMID 33504604, 2021). "The apolipoprotein E (APOE) ε4 allele is a risk factor for Alzheimer’s disease (AD) that has been linked to changes in brain structure and function as well as to different biological subtypes of the disease." (PMID 34679423, 2021). "The most powerful predictor of Alzheimer’s disease at this time is ApoE E4 gene variation: one or two copies of ApoE is associated with an increased risk of disease onset." (PMID 33514397, 2021). "ApoE genotype and participant age are established risk factors for Alzheimer’s disease and brain amyloidosis." (PMID 33933117, 2021). "The APOE ɛ4 allele is associated with a risk of Alzheimer’s disease in the elderly, with the association being pronounced in females." (PMID 32954402, 2021). "Amyloid plaque formation is a primary diagnostic measure of Alzheimer’s disease with both APOE and TREM2 linked to amyloid deposition." (PMID 34707490, 2021). "For instance, the APOE e4 allele is traditionally associated with adverse health outcomes, including an increased risk of Alzheimer's disease, cardiovascular disease, and reduced life expectancy, while the e2 allele confers protection." (PMID 34038024, 2021). "There is evidence that the T allele of rs405509 located in the apolipoprotein E (APOE) promotor region is a risk factor for Alzheimer’s disease (AD)." (PMID 34177454, 2021). "APOE has been implicated in various neuropathological cascades relevant to Alzheimer’s disease, including alterations in cerebral glucose metabolism, amyloidosis, tau tangle pathology, microglial activation and neurodegeneration." (PMID 34189460, 2021). "For example, the ε4 allele of apolipoprotein E (ApoE) has been reported to increase the risk of Alzheimer’s disease, cognitive decline, and coronary artery disease." (PMID 34647905, 2021).